RNU6-946P (RNA, U6 small nuclear 946, pseudogene)
Gene: Small nuclear RNA gene on chromosome 10 (26,790,540 to 26,790,646, reverse strand). Ensembl gene ENSG00000206605.
Homologues: Orthologues: chimpanzee U6 (100% identical), macaque U6 (95% identical), dog U6 (83% identical). Paralogues in human: RNU6-1011P (91% identical), RNU6-842P (91% identical), RNU6-1158P (90% identical), RNU6-12P (90% identical), RNU6-13P (90% identical), RNU6-166P (90% identical), RNU6-25P (90% identical), RNU6-26P (90% identical), RNU6-31P (90% identical), RNU6-32P (90% identical), RNU6-38P (90% identical), RNU6-41P (90% identical), and 1288 more.